SDCBP2 (syndecan binding protein 2)
Description:
Binds phosphatidylinositol 4,5-bisphosphate (PIP2). May play a role in the organization of nuclear PIP2, cell division and cell survival.
Synonyms: SITAC; SITAC18; ST-2; ST2
Tractability: Antibody: UniProt places it where antibodies can reach, with high confidence; its Gene Ontology location is reachable by antibodies, with high confidence. PROTAC: its protein half-life has been measured.
Gene: Protein-coding gene on chromosome 20 (1,309,909 to 1,329,211, reverse strand). Ensembl gene ENSG00000125775.
Subcellular location: Cytoplasm; Nucleus, nucleolus; Nucleus, nucleoplasm; Cell membrane; Nucleus speckle
Subcellular location (Human Protein Atlas): Nucleoplasm; Cytosol; Golgi apparatus
Gene Ontology:
Molecular function: identical protein binding; phosphatidylinositol-4,5-bisphosphate binding; protein binding; protein heterodimerization activity; protein homodimerization activity
Biological process: cell population proliferation; intracellular signal transduction; intracellular transport; nervous system development
Cellular component: cytoplasm; cytosol; extracellular exosome; nuclear speck; nucleolus; nucleoplasm; plasma membrane
Genetic constraint (gnomAD): Loss-of-function variants: 25 observed, 26.38 expected, observed/expected ratio (o/e) 0.95, 90% interval 0.69 to 1.32. The upper end of that interval is the gene's LOEUF score, 1.32, which puts it in group 5 of 6, group 1 being the genes least tolerant of losing a copy. Missense variants: 396 observed, 367.53 expected, observed/expected ratio (o/e) 1.08, 90% interval 0.99 to 1.17. Synonymous variants: 164 observed, 150.11 expected, observed/expected ratio (o/e) 1.09, 90% interval 0.96 to 1.24.
Homologues: Orthologues: chimpanzee SDCBP2 (97% identical), macaque SDCBP2 (96% identical), pig SDCBP2 (83% identical), guinea pig SDCBP2 (82% identical), rat Sdcbp2 (80% identical), mouse Sdcbp2 (79% identical), dog SDCBP2 (76% identical), rabbit SDCBP2 (76% identical), tropical clawed frog sdcbp2 (60% identical), zebrafish sdcbp2 (59% identical), zebrafish sdcbp (52% identical), Drosophila melanogaster X11Lbeta (22% identical), and 1 more. Paralogues in human: SDCBP (58% identical), APBA1 (25% identical), APBA3 (24% identical), APBA2 (21% identical).
Diseases named in the same sentence as SDCBP2 in open-access papers:
SDCBP2 is named in the same sentence as 21 diseases in open-access papers, as found by Europe PMC text mining. Sharing a sentence is not in itself a finding about the gene and the disease. The quoted sentences say what the papers report.
acute myeloid leukemia (1 paper, 2025). Acute myeloid leukemia (AML) is a group of neoplasms arising from precursor cells committed to the myeloid cell-line differentiation. "Studies have found that SDCBP2 expression is increased in patients with acute myeloid leukemia (AML), and downregulating SDCBP2 expression can inhibit the proliferation of AML cells and induce their differentiation." (PMID 41409290, 2025).
colorectal cancer (1 paper, 2018). A primary or metastatic malignant neoplasm that affects the colon or rectum. "Similarly, for PYY-CKAP2 and SDCBP2-DAP3 gene pairs, up-regulation of CKAP2, DAP3 and down-regulation of PYY, SDCBP2 contribute to the reversal REO in colorectal cancer samples." (PMID 29378509, 2018).
lung adenocarcinoma (1 paper, 2025). A carcinoma that arises from the lung and is characterized by the presence of malignant glandular epithelial cells. "To investigate the role of SDCBP2 in ferroptosis, we measured reactive oxygen species (ROS) and glutathione (GSH) levels in lung adenocarcinoma cell lines (A549 and PC-9)." (PMID 41409290, 2025).
cancer (2 papers, 2018 to 2025). A tumor composed of atypical neoplastic, often pleomorphic cells that invade other tissues. "Analysis of the TCGA pan-cancer dataset revealed that SDCBP2 is a prognostic risk gene only in LUAD." (PMID 41409290, 2025). "We utilized the TIMER database to analyze the expression of SDCBP2 in the TCGA pan-cancer dataset." (PMID 41409290, 2025).
tumor (1 paper, 2022). "Only AKR7A3 and SDCBP2 were consistently upregulated strictly in tumor cells." (PMID 35995947, 2022).
SDCBP2 also shares sentences with these, for which no sentence is quoted: bile duct cancer (1 paper); cervical cancer (1); Colon Cancer (1); emphysema (1); epidermodysplasia verruciformis (1); glioblastoma (1); head and neck cancer (1); Kidney Chromophobe (1); Lung Squamous Cell Carcinoma (1); ovarian carcinoma (1); pheochromocytoma-paraganglioma (1); prostate carcinoma (1); rectal cancer (1); Sepsis (1); skin tumors (1); thyroid cancer (1).